EPO (erythropoietin)
Diseases named in the same sentence as EPO in open-access papers (continued):
Sharing a sentence is not in itself a finding about the gene and the disease.
diabetes (continued). "In a previous study, recombinant human erythropoietin (rhEPO) was shown to prevent stage 2 PU formation and to impede degeneration of cutaneous sensory nerves in a long-term mouse experimental diabetes." (PMID 25422898, 2014). "Recombinant human erythropoietin (rhEPO) has been shown to protect the skin against PUs developed in animal models of long-term diabetes." (PMID 25422898, 2014). "Diabetes significantly increased EPO mRNA levels 1.49-fold after 4 weeks and 1.51-fold after 12 weeks (p<0.05)." (PMID 23878504, 2013). "In this study, the EPO mRNA levels were elevated in the rat retina at 4 and 12 weeks of diabetes, possibly to protect the neural and vascular cells in the retina." (PMID 23878504, 2013). "Diabetes inhibits erythropoietin- and morphine-induced activation of PI3K-Akt, ERK 1/2, and inhibition of GSK-3beta, and attenuates PostC." (PMID 22239823, 2012). "The EPO treatment duration in our study was rather longer to exert its cardiac protective effects in diabetes." (PMID 22954171, 2012). "In general, there are several associated factors that make normalization of blood pressure levels difficult to attain in PD patients, including the presence of diabetes mellitus, aging, and the use of erythropoietin." (PMID 22649498, 2012). "EPO also can protect dorsal root ganglion neurons in animal models of diabetes mellitus with streptozotocin through pathways that activate Akt." (PMID 23109841, 2012). "Although a chronic rat model that tested the effect of EPO was used in the present study, there were some reports showing that protective cellular signaling of EPO treatment was disturbed in diabetes." (PMID 22954171, 2012). "In models of experimental diabetes, EPO preserves brain EC integrity that is necessary for protection of the neurovascular unit through Wnt1, since administration of anti-Wnt1 neutralizing antibodies or gene silencing of Wnt1 block EPO protection." (PMID 23109841, 2012). "We were unable to account for the differences observed in our clinical trial on the basis of age, gender, diabetes mellitus, bleeding times, hematocrit levels, or weekly doses of recombinant human erythropoietin." (PMID 20368925, 2009). "Diabetes (as a primary renal diagnosis and concomitant disease) was found to influence Hb to higher values and EPO delivery to a lower dose." (PMID 19077225, 2008). "In multivariate analysis, diabetes was found to influence Hb towards a higher level (p = 0.004) and EPO requirements towards lower doses (p = 0.0004)." (PMID 19077225, 2008). "As noted in the first limitation, the use of EPO as one of the inclusion criteria may limit the representativeness of the broader Taiwanese population with diabetes and CKD stage 5." (PMID 40611400, 2025). "When combining PDR with ESRD within the mixed types of diabetes in the European population, the effect of rs1617640 at EPO gene was regarded as highly credible under the allelic model (T vs. G), dominant model (TT + TG vs. GG), recessive model (TT vs. TG + GG), and homozygous model (TT vs. GG)." (PMID 40116328, 2025). "In patients with diabetes, the proximal tubules become overburdened due to excessive glucose reabsorption, leading to dysfunction in adjacent fibroblasts and a subsequent reduction in erythropoietin production." (PMID 40076724, 2025). "This highlights the complex nature of EPO’s influence on the retina, particularly in patients with advanced diabetes, where excessive angiogenesis may lead to proliferative diabetic retinopathy." (PMID 41196916, 2025). "Albuminuria has been reported to reflect decreased erythropoietin production in individuals with diabetes, which may lead to decreased hemoglobin production." (PMID 37955878, 2024). "Notably, hemoglobin was lower in patients with DN compared to NDRD, potentially due to the long course of diabetes, disorder of splanchnic innervation, or impaired release of erythropoietin (EPO)." (PMID 38344659, 2024).
diabetes (continued). "Some studies have demonstrated a very low prescription rate of targeted medications within specific CKD patient: for exemple RASi for patients with diabetes and proteinuria, iron and erythropoietin for anaemic patients, statin for patients with coronary artery disease." (PMID 32131742, 2020). "Several proinflammatory cytokines could inhibit synthesis or activity of erythropoietin and diabetes has been considered a proinflammatory state." (PMID 32185232, 2020). "A more clinically oriented inquiry may explain why the peritoneal dialysis patients with diabetes showed a stronger response to the increase in erythropoietin dosage and Hct levels in terms of reducing cardiovascular risk." (PMID 33331829, 2020). "A growing literature argues for a critical role of EPO in diabetes and its complications." (PMID 31316151, 2019). "Inappropriately low EPO levels were observed in 73% of anemic patients and 59% of anemic patients even without CKD, suggesting that EPO deficiency precedes the onset of CKD in diabetes mellitus." (PMID 31619722, 2019). "In addition, a few papers demonstrated that sodium-glucose transporter (SGLT) 2 inhibitors, a new class of diabetes medication, elevate EPO levels." (PMID 31619722, 2019). "EPO reportedly has beneficial effects on obesity and diabetes mellitus." (PMID 28288167, 2017). "Furthermore, a history of myocardial infarction or diabetes mellitus was more frequently observed with increasing EPO quintiles." (PMID 25915923, 2015). "Among general medical treatment options, development of new pharmaceutical compounds, such as recombinant human erythropoietin, as well as better care of patients with diabetes and cardiovascular complications can be considered to have beneficial effects on morbidity and mortality." (PMID 22747751, 2012). "For example, EPO acting through the IRR has been shown to improve recovery and function from nerve injury in a variety of preclinical models, including the small-fiber neuropathy caused by uncontrolled diabetes." (PMID 23304492, 2012). "However, in conditions such as sickle cell disease, glucose‐6‐phosphate dehydrogenase deficiency, hemodialysis, recent bleeding or transfusion, and erythropoietin therapy, the diagnosis of diabetes must be based on the measurement of venous plasma glucose levels, and HbA1c cannot be used." (PMID 38571669, 2024). "Therefore, this presents an opportunity to deliver a systematic review that will yield a comprehensive synthesis obtained from the available collected studies that previously reported on the red blood cell indices and concentration of EPO and eNOS during pre-diabetes." (PMID 36827500, 2023). "In patients with diabetes in maintenance HD treatment, however, the utility of HbA1c has been questioned since it is altered by several factors such as anemia, erythrocyte turn-over and erythropoietin treatment; hence, alternative laboratory indices have been proposed." (PMID 35329847, 2022). "Furthermore, EPO has been noted to exert direct protective effects on pancreatic β islet cells in diabetes mouse models, and, in neonatal porcine islet cells, EPO's anti-apoptotic effect occurs through upregulation of Bcl-2 mRNA and downregulation of Bax and caspase-3 mRNA." (PMID 33796104, 2021). "However, blood glucose at the end of the study was higher than expected (Diabetic 31.6 ± 0.7mmol/L and Diabetic + EPO 30.1 ± 1.3 mmol/L) and more typical of severe diabetes with irreparable damage to the pancreatic β cells likely in spite of EPO administration." (PMID 30597853, 2018). "These may be the mechanisms of action of EPO in diabetes, but it requires further investigation." (PMID 30597853, 2018). "However, chronic EPO treatment to patients with diabetes is not acceptable since it is associated with thromboembolic episodes and increased blood pressure." (PMID 23577069, 2013).
diabetes (continued). "This is based, in part, on the clinical emergence of new EPO orthologues and mimetics, and on EPO's ability to cytoprotect select non-hematopoietic tissues from ischemic injury; to regulate select immune responses; and to modulate susceptibility to diabetes." (PMID 22808010, 2012). "We also highlight the emerging EPO-EPOR-RUNX1 axis in metabolic disorders, such as obesity, diabetes, and related conditions." (PMID 39996752, 2025). "These factors include age, gender, diabetes, dialysis duration, nutritional status, hepatitis C virus (HCV) infection, body mass index (BMI), dialysis method, erythropoietin treatment, and genetic factors." (PMID 40775743, 2025). "As its name suggests, HIF-1 is induced by small vessel hypoxia in the retina created by diabetes and then mediates retinal neovascularization through the release of VEGF and erythropoietin." (PMID 41472886, 2025). "The scientific literature highlights the biological action of EPO and GLA obtained from seeds in the treatment of diabetes and related conditions." (PMID 41157076, 2025). "Other diseases such as diabetes, chronic infections, inflammation, and CKD also affect RBC proliferation, erythropoietin production, androgen secretion, and myelodysplasia." (PMID 36900859, 2023). "Independent predictive factors of VTE (diabetes, ECOG performance status, erythropoietin-stimulating agent use, dexamethasone use, and VTE history or family history of thrombosis) were identified and merged to develop the RAM." (PMID 37794471, 2023). "Risk factors for IDH identified in this study include female gender, advanced age, diabetes, acidosis, and for IDHT included middle age, use of ≥3 antihypertensive drugs, lower predialysis creatinine, frequent erythropoietin use and male gender." (PMID 38322382, 2021). "When compared with that in the normal control group, the protein expression of EPO and EPOR in the retina in the diabetic group was up-regulated with the progression of diabetes." (PMID 30401898, 2019). "Diabetes decreases the antioxidant ability of heart tissue by decreasing plasma and cardiac tissue T.SOD levels and downregulating cardiac tissue EPO and VEGF mRNA expressions, thereby increasing the major cardiac markers plasma troponin I and CK-MB." (PMID 30510626, 2018). "CCI: Charlson Comorbidity Index, DM: diabetes mellitus, EPO: erythropoietin, NHI: National Health Insurance." (PMID 26469976, 2015). "Hypoxia is present from the early stages of diabetes as affinity and static hypoxia, possibly with secretion of vascular endothelium growth factor (VEGF) and erythropoietin (EPO)." (PMID 24782919, 2014). "Moreover, McVicar and coworkers have recently demonstrated that treatment with an EPO-derived peptide in fully established diabetes could significantly protect against neuroglia and vascular degenerative pathology without altering hematocrit or exacerbating neovascularization (2011)." (PMID 24066292, 2013). "The significant risk variables for VTE in the derivation obtained based on the univariate analysis included diabetes, ECOG performance status, the use of an erythropoietin-stimulating agent, the use of dexamethasone, and a family history of thrombosis or a history of VTE." (PMID 37794471, 2023). "It has been reported that patients with diabetes and ESRD, GA could be a better glycemic index than HbA1c in not being affected by the lifespan of red blood cells, use of iron and/or erythropoietin therapy." (PMID 35329847, 2022). "However, in an early diabetes animal model and DME patients, exogenous EPO administration not only protected against the VEGF-induced permeability of the BBB and restored the tight junction proteins, but it also counteracted neurodegeneration." (PMID 34621759, 2021). "Some studies have shown that reduced erythropoietin production and anaemia happen earlier in people with diabetes and kidney disease than in those with kidney disease and no diabetes." (PMID 33628496, 2021).
diabetes (continued). "In diabetics and CKD patients, several molecular pathways linking chronic inflammation and anisocytosis have been proposed: shortened erythrocyte lifespan, inhibited erythropoietin response and impaired iron metabolism." (PMID 33266382, 2020). "Median (IQR) EPO levels (mIU/mL) in patients with vs. without diabetes mellitus were 15.20 (12.50–29.90) vs. 13.85 (9.50–23.80) (p = 0.097) in female and 16.60 (8.00–28.30) vs. 13.75 (8.95–20.15) (p = 0.220) in male." (PMID 33330669, 2020). "EPO/EPOR signaling plays a protective role in multiple organs and tissues such us adipose tissue, pancreas, heart, skeletal muscle,and nervous system and pathological condition such as obesity, diabetes, and cancer." (PMID 31915448, 2019). "Results of these studies show that hypoxia is involved in cerebral edema, tumorigenesis, myocardial ischemia and diabetes in human being, and some genes including Endothelin 1 (EDN1), Erythropoietin (EPO) and Aldosterone synthase (CYP11B2) are reported as the key genes of hypoxia adaptation." (PMID 31239472, 2019). "The expression of factors such as HIF-1alpha, VEGF, EPO, EPOR, GFAP and vimentin, was up-regulated with the progression of diabetes in the diabetic rat retinas compared to the expression in normal control retinas, whereas the expression of GS and GLAST was down-regulated." (PMID 30401898, 2019). "Changes in EPO and EPOR appeared 2 weeks after diabetes onset." (PMID 30401898, 2019). "Data from as early as day 1 of the water maze test showed that 10 weeks of diabetes (with or without EPO treatment) resulted in impaired cognitive performance (i.e., escape latency and distance) compared to controls." (PMID 30597853, 2018). "As can be seen, this difference in swimming speed on day 5 was due a recovery in swimming speed of control and EPO-treated diabetics compared to days 2–4, rather than a decrease in swimming speed of the diabetics." (PMID 30597853, 2018). "Continuous NRI and IDI revealed that the biomarkers that are less influenced by sepsis—TIMP-2, NAG and EPO—improved prediction of severe AKI in the septic population when added to the clinical model, which incorporated age, sex, complication of diabetes, medical admission and serum creatinine." (PMID 25524453, 2014). "Moreover, vitreous levels of EPO and VEGF correlated with the HbA1c in patients with PDR implicating the effect of diabetes control on PDR progression." (PMID 24066292, 2013). "The effect of SGLT2i on improving cardiovascular health in patients with CVD, with or without type 2 diabetes mellitus, is a combination of multiple mechanisms, including promoting vascular endothelial regeneration and enhancing liver erythropoietin production function and renal filtration." (PMID 39539627, 2024). "The DAPA-HF data demonstrates this observation of SGLT-2i independent of diabetes and the potential increase in erythropoietin (EPO) that could be behind improving renal function." (PMID 34754647, 2021). "In rodents, EPO protects against streptozotocin (STZ) induced type 1 diabetes by reversing STZ-mediated β-cell destruction, an activity that is abrogated with EpoR knockout in pancreatic islet, and is protective against diabetes in the db/db mouse model of type 2 diabetes." (PMID 24918289, 2014). "Increased expression of EPO and IGFBP3 and increased VEGF protein levels may be protective responses to damage caused by diabetes, but these responses may not provide sufficient protection." (PMID 23878504, 2013). "We identified patients with diabetes and CKD stage 5 not on dialysis who received erythropoietin (erythropoietin‐stimulating agent), a drug reimbursed for patients with an estimated glomerular filtration rate <15 mL/min/1.73 m2." (PMID 40611400, 2025). "Chronic inflammation and fibrosis in diabetes and CKD may impair EPO production by transforming renal erythropoietin-producing cells (REPs) into non-functional myofibroblasts." (PMID 40512678, 2025).
diabetes (continued). "Study showed that SGLT2 inhibitors could raise the hematocrit, even in those without diabetes (as seen in DAPA-HF); it is speculated that these agents may promote erythropoiesis via enhanced EPO secretion by the kidney." (PMID 33779938, 2022). "In this study we revealed that CEPO, a carbamoyl derivative of EPO that does not affect erythropoiesis, attenuated myocardial pathological damage, at least in part through the activation of the PI3K/Akt signaling pathway, which regulates myocardial cell apoptosis in diabetes mellitus." (PMID 24137228, 2013).